CDH3 (cadherin 3)
Description:
Cadherins are calcium-dependent cell adhesion proteins. They preferentially interact with themselves in a homophilic manner in connecting cells; cadherins may thus contribute to the sorting of heterogeneous cell types.
Synonyms: CDHP; PCAD; HJMD
Tractability: Small molecule: a structure with a bound ligand is known. Antibody: a drug acting on it is in phase 1 trials; its Gene Ontology location is reachable by antibodies, with high confidence; UniProt places it where antibodies can reach, with medium confidence; UniProt predicts a signal peptide or a membrane-spanning region; the Human Protein Atlas places it where antibodies can reach. PROTAC: ubiquitination databases record sites on it.
Target class: Adhesion
Gene: Protein-coding gene on chromosome 16 (68,636,189 to 68,727,468, forward strand). Ensembl gene ENSG00000062038.
Subcellular location: Cell membrane
Subcellular location (Human Protein Atlas): Cell Junctions; Plasma membrane
Pathways (Reactome):
Cell-Cell communication: Adherens junctions interactions
Gene Ontology:
Molecular function: beta-catenin binding; cadherin binding; calcium ion binding
Biological process: hair cycle process; hair follicle maturation; keratinization; negative regulation of timing of catagen; negative regulation of transforming growth factor beta receptor signaling pathway; positive regulation of canonical Wnt signaling pathway; positive regulation of insulin-like growth factor receptor signaling pathway; positive regulation of keratinocyte proliferation; positive regulation of melanin biosynthetic process; retina homeostasis; adherens junction organization; calcium-dependent cell-cell adhesion; cell adhesion; cell migration; cell morphogenesis; cell-cell adhesion mediated by cadherin; cell-cell junction assembly; cell-cell adhesion; homophilic cell-cell adhesion
Cellular component: cell junction; plasma membrane; adherens junction; catenin complex; cytoplasm; membrane
Genetic constraint (gnomAD): Loss-of-function variants: 54 observed, 82.27 expected, observed/expected ratio (o/e) 0.66, 90% interval 0.53 to 0.82. The upper end of that interval is the gene's LOEUF score, 0.82, which puts it in group 3 of 6, group 1 being the genes least tolerant of losing a copy. Missense variants: 1,054 observed, 1,119.8 expected, observed/expected ratio (o/e) 0.94, 90% interval 0.89 to 0.99. Synonymous variants: 446 observed, 453.76 expected, observed/expected ratio (o/e) 0.98, 90% interval 0.91 to 1.06.
Gene-disease validity (ClinGen):
ClinGen rates the evidence that CDH3 causes each of these diseases.
EEM syndrome (autosomal recessive): Definitive. EEM syndrome is characterized by the association of ectodermal dysplasia, ectrodactyly, and macular dystrophy.
Homologues: Orthologues: chimpanzee CDH3 (99% identical), macaque CDH3 (96% identical), pig CDH3 (86% identical), dog CDH3 (86% identical), rabbit CDH3 (83% identical), rat Cdh3 (82% identical), guinea pig CDH3 (82% identical), mouse Cdh3 (82% identical), zebrafish cdh1 (48% identical), zebrafish cdh31 (43% identical), zebrafish cdh28 (34% identical), zebrafish cdh30 (33% identical), and 1 more. Paralogues in human: CDH1 (57% identical), CDH2 (44% identical), CDH4 (43% identical), CDH15 (36% identical), CDH7 (32% identical), CDH11 (30% identical), CDH18 (30% identical), CDH6 (29% identical), CDH13 (29% identical), CDH9 (29% identical), CDH12 (29% identical), CDH20 (28% identical), and 21 more.
Diseases named in the same sentence as CDH3 in open-access papers:
CDH3 is named in the same sentence as 152 diseases in open-access papers, as found by Europe PMC text mining. Sharing a sentence is not in itself a finding about the gene and the disease. The quoted sentences say what the papers report.
breast carcinoma (95 papers, 2008 to 2025). "We found that CHAI was able to identify a CDH3-enriched cell population which has been linked to leading cell migration in breast cancer." (PMID 39207729, 2024). "Loss of DNA methylation in the CDH3 gene promoter results in the overexpression of P-cadherin in colorectal and breast carcinomas, which decreased cell polarity and promotes the invasion and migration of colorectal and breast cancer cells." (PMID 37077808, 2022). "Increased levels in TOP1 and CDH3 were validated in a large population-based series of breast cancer patients with a BRCA1/2 mutation." (PMID 27566577, 2016). "In previous studies, an increased level of CDH3 has been detected in a small cohort of BRCA1-deficient breast cancer, as well as in nipple aspirate fluid and serum obtained from women with basal-like breast tumors." (PMID 27566577, 2016). "The induction of CDH3 promoter activity by C/EBPβ was also confirmed by reporter assays, as well as its expression association with worse prognosis of breast cancer patients." (PMID 23405208, 2013). "Therefore, we here applied immunohistochemistry for verification of increased expression of TOP1 and CDH3 in BRCA1-deficient breast carcinomas." (PMID 27566577, 2016). "We demonstrate that TOP1 and CDH3 are closely associated to BRCA1-deficient breast cancer." (PMID 27566577, 2016). "Similarly, an independent association of CDH3 expression for BRCA1/2-related breast carcinomas was found (adjusted OR 2.44; 95% CI, 1.08–5.49, p = 0.032)." (PMID 27566577, 2016). "Research has also shown that CDH3 promotes tumorigenesis in gastric cancer, pancreatic cancer, and breast cancer, while it inhibits tumorigenesis in HCC and melanoma." (PMID 39159001, 2024). "In breast cancer, overexpression of CDH3 will increase cell invasion and migration and increase MMP1 and MMP2 expression." (PMID 37151391, 2023). "In breast cancer, overexpression of CDH3 is connected to more aggressive tumor behavior and poor patient survival." (PMID 37620794, 2023). "STEMVAC is a multi-Ag plasmid DNA vaccine encoding Th1 epitopes of CD105, Yb-1, SOX2, CDH3, and MDM2: five important TAAs associated with cancer stem cells and the EMT process in breast cancer." (PMID 36679991, 2023). "For example, DNA hypomethylation of the CDH3 gene promoter, partly due to overexpression of P-cadherin, can induce cell invasion, motility, and migration as well as disillusioning patients’ outcomes in colorectal and breast carcinomas." (PMID 35810299, 2022). "LIP was furthermore shown to upregulate the expression of the chemokine receptor CXCR4 and the pro-invasive CDH3/P cadherin in breast cancer cells, both known drivers of metastasis." (PMID 35042889, 2022). "CDH3 is highly expressed and promotes tumorigenesis in pancreatic cancer, gastric cancer, and breast cancer, while it is expressed at low levels and suppresses tumorigenesis in non-small-cell lung cancer, hepatocellular carcinoma and thyroid cancer." (PMID 35787690, 2022). "By the analysis of a previously published gene expression profile of a data set of BCC lines (GEO accession number: GSE6569), we observed that CDH3 expression correlates with the sensitivity/resistance of breast cancer cells to dasatinib." (PMID 30404626, 2018). "Up-regulation of CDH3 expression has been reported in esophageal, pancreatic, bladder, prostate, melanoma, and breast cancer." (PMID 29142905, 2017). "When TOP1 and CDH3 were combined, there was a significant association between breast carcinomas with positive TOP1 and CDH3 and BRCA1/2 mutations (adjusted OR 5.05; 95% CI, 1.75–14.6, p = 0.003)." (PMID 27566577, 2016). "Multiple logistic regression was performed to estimate the predictive effects of TOP1 or CDH3 for BRCA1/2-related breast carcinomas when adjusted for triple negative breast cancer and age." (PMID 27566577, 2016).
breast carcinoma (continued). "With regard to CDH3, a significant difference was found among the three groups with 76% of BRCA1-related, 37% of BRCA2-related and 22% of sporadic breast carcinomas being CDH3 positive (p < 0.001)." (PMID 27566577, 2016). "Of note, the rates of TOP1 and CDH3 positivity were the highest in BRCA1-related breast carcinomas (48%) followed by BRCA2-related (24%) and sporadic breast carcinomas (7%)." (PMID 27566577, 2016). "We showed that expression of TOP1 and CDH3 was significantly increased in human BRCA1-related breast carcinomas relative to sporadic cases (p = 0.002 and p < 0.001, respectively)." (PMID 27566577, 2016). "There was a significant difference between BRCA1-related and sporadic breast carcinomas in terms of CDH3-positive cases (p < 0.001)." (PMID 27566577, 2016). "In breast cancer, several lines of evidence have implicated overexpression of EZH2 and repression of tumor suppressors such as KRT5, KRT6, CDH3, RAD51 paralogs, CDKN1C, FOXC1, Wnt/β-catenin signaling (c-Myc, Cyclin D1, Axin2), RKIP and KLF2." (PMID 27835578, 2016). "CDH3, a plasma membrane protein, is involved in cell adhesion and has been proposed as a tissue marker in human BRCA1-deficient breast cancer as well as a serum marker in basal-like breast cancer." (PMID 27566577, 2016). "Two proteins highly abundant in the BRCA1-deficient secretome, namely CDH3 and TOP1, were selected for validation in tumor tissue samples of breast cancer patients." (PMID 27566577, 2016). "The present work demonstrates for the first time that P-cadherin and C/EBPβ co-localize in the same breast cancer cells, and that there is a physical interaction between this transcription factor and CDH3 gene promoter." (PMID 23405208, 2013). "In 2010, we described a regulatory mechanism whereby a selective ER-downregulator is able to up-regulate P-cadherin expression in MCF-7/AZ breast cancer cells through chromatin remodelling at CDH3 promoter level." (PMID 23405208, 2013). "Taken together, our data show that CDH3 is a newly defined transcriptional target gene of C/EBPβ isoforms in breast cancer, and we also identified the binding sites that are relevant for this activation." (PMID 23405208, 2013). "We demonstrated that C/EBPβ is co-expressed with P-cadherin in breast cancer cells and all the three isoforms function as transcriptional regulators of the CDH3 gene, directly interacting with specific regions of its promoter." (PMID 23405208, 2013). "Finally, we went to evaluate if sP-cad was also required for the induction of paracrine anoikis resistance of breast cancer cells, by treating BT20 breast cancer cells with the conditioned media of MCF10A-Plk4p53KO upon CDH3 silencing." (PMID 36797240, 2023). "Additionally, CDH3 expression was able to predict sensitivity/resistance to dasatinib treatment, both in breast cancer and in prostate cancer cell models." (PMID 30404626, 2018). "Furthermore, MRTF/SRF target genes' expression was positively associated with basal marker (CDH3), but negatively correlated with luminal marker (ESR1), suggesting that the activity of MRTF/SRF is higher in basal-like breast cancers than other subtypes." (PMID 26885614, 2016). "We report that TOP1 and CDH3 were expressed to a higher extent in BRCA1-related breast carcinomas relative to sporadic breast carcinomas, highlighting their potential clinical usefulness for breast cancer detection in women with a BRCA1 mutation." (PMID 27566577, 2016). "Topoisomerase I (TOP1) and P-cadherin (CDH3) expression was investigated by immunohistochemistry on tissue microarrays of a large panel of 253 human breast carcinomas with and without BRCA1/2 mutations." (PMID 27566577, 2016). "We demonstrated increased CDH3 levels in a large panel of human BRCA1-related breast carcinomas." (PMID 27566577, 2016).
breast carcinoma (continued). "As a first step to evaluate clinical relevance, we analyzed protein expression of topoisomerase I (TOP1) and P-cadherin (CDH3) in a large panel of breast cancer tissues from BRCA1/2 mutation carriers and women without a hereditary predisposition." (PMID 27566577, 2016). "In our list of candidate targets, some genes including, for example, the gamma-aminobutyric acid receptor subunit pi (GABRP) and cadherin 3, type 1 (CDH3), were characterized by high expression in breast cancer versus normal tissues, but with relatively high levels in normal breast." (PMID 26700623, 2016). "In conclusion, this study contributes to clarify the individual role of C/EBPβ proteins in breast cancer-related CDH3/P-cadherin gene, as well as to expand the limited characterization of the mechanisms and players that regulate this pro-invasive protein in breast cancer." (PMID 23405208, 2013). "We conclude that CDH3 is a newly defined transcriptional target gene of C/EBPβ in breast cancer." (PMID 23405208, 2013). "Since the distinct C/EBPβ isoforms have been documented has having different functions in cancer gene activation and in a cell-specific context, we co-transfected LAP1, LAP2 and LIP together with the different mutants of CDH3 promoter in both breast cancer cell lines." (PMID 23405208, 2013). "In fact, a significant correlation was recently described between P-cadherin expression and hypomethylation of a specific region of the CDH3 promoter, suggesting an important regulatory role for cytosine methylation in the aberrant expression of P-cadherin in breast cancer." (PMID 22973534, 2012). "However, data concerning CDH3 gene regulation in breast cancer is still very limited." (PMID 23405208, 2013). "Moreover, the aberrant expression of CDH3 in breast cancer might be regulated by gene promoter hypomethylation." (PMID 20799942, 2010). "Hierarchical clustering of NCS‐1 and breast cancer molecular markers showed a positive correlation with basal and proliferative markers, such as KRT5, 14 and 17, CDH3, FOXC1, FOXM1, EGFR, and MKI67." (PMID 31647602, 2020). "Of 195 breast cancer samples with TOP1 and CDH3 available, 57 samples were positive for TOP1 and CDH3 and 138 samples were TOP1 and/or CDH3 negative (79 positive for either of the two markers and 59 samples negative for both markers)." (PMID 27566577, 2016). "Protein expression of CDH3 and TOP1 was analysed in a panel of 253 human breast carcinomas comprising 102 BRCA1-related, 49 BRCA2-related and 102 sporadic breast carcinomas." (PMID 27566577, 2016). "Accordingly, we demonstrated that the inhibition of CDH3, HIF-1α, GLUT1 and CAIX in basal-like breast cancer cells significantly reduces their MFE, an important measure of breast cancer stem cell activity." (PMID 25269858, 2014). "The list of these genes includes not only a large number of known breast cancer genes (e.g. CDH1, CDH3, BMP4, MTAP, CDKN2B), revealed by previous studies using breast tumor tissues and breast cancer cell lines but also novel genes." (PMID 24885402, 2014). "In fact, in order to demonstrate if there was a physical interaction between C/EBPβ proteins and CDH3 promoter in these specific binding sites, ChIP has been performed in MCF-7/AZ breast cancer cells." (PMID 23405208, 2013). "More recently, we have studied the expression of five different BCSC markers (CD44, integrin subunit α6, cadherin-3, EpCAM, and ALDH1) and found significant enrichment for each biomarker in human breast cancer brain metastasis when compared with unmatched primary tumours." (PMID 35326385, 2022). "The prognostic value of CDH3, predictive of shorter OS in independent cohorts of GBM patients, is concordant with the results obtained in vivo, and fits well with previous reports in breast cancer and lung cancer." (PMID 34919784, 2022).
breast carcinoma (continued). "In addition, we verified the expression of 3 differential proteins by immunohistochemistry and found that CDH3 and EIF4G1 were significantly higher in breast cancer tissues." (PMID 35787690, 2022). "Particularly, the negative association between the genes CDH2, CDH3, CDH11, CDH13, CDH18 and NAT1 N-acetylation activity supports observations of high NAT1 expression in breast cancer and increased metastasis." (PMID 35046826, 2021). "In the real data analyses we observed many pairs might have a gene in common, for instance, SPDEF in the breast cancer dataset and BCLAF1 and CDH3 in the lung cancer dataset." (PMID 32334509, 2020). "Moreover, we also showed that CDH3 silencing led to a decrease of the mRNA levels of GLUT1 and CAIX in breast cancer cell lines in vitro." (PMID 31010154, 2019). "By real-time PCR, we could observe that CDH3 silencing led to a statistically significant downregulation of GLUT1 and CAIX mRNA in BT20 breast cancer cells (p < 0.05)." (PMID 25269858, 2014). "For cadherin 3 (CDH3), the expression of which is detected by the sense-AFAS probe pair X63629-03, a previous study showed that its expression is increased in breast cancer." (PMID 21575255, 2011). "Moreover, the effects of CDH3 are dependent on the expression of CDH1 which is generally low to absent in our canine mammary tumor cell lines with low basal Wnt activity." (PMID 31105876, 2019). "The CDH3-specific clone was shown to specifically kill an HLA-A2+ breast cancer cell line (MCF-7), and not an HLA-A2+ metastatic melanoma cell line (MM909.24; obtained from the Center for Cancer Immune Therapy, Herlev Hospital, Copenhagen, Denmark) in a 51Cr-release assay after 4 h." (PMID 26826277, 2016). "Interestingly, we found that HIF-1α stabilization promotes membrane P-cadherin expression in breast cancer cells, although no alterations were detected in CDH3 mRNA levels after CoCl2 treatment." (PMID 25269858, 2014). "Additionally, we established a direct link between P-cadherin overexpression and the lack of oestrogen receptor (ER)-signalling in breast cancer cells, categorizing CDH3 as a putative ER-repressed gene." (PMID 23405208, 2013). "CDH3 and EIF4G1 were expressed at significantly higher levels in breast cancer tissues than in paracancerous tissues, but CASP7 was not." (PMID 35787690, 2022).
melanoma (29 papers, 2007 to 2025). A malignant, usually aggressive tumor composed of atypical, neoplastic melanocytes. "A whole-genome study of 183 melanomas found RAF1 fusions in two melanomas (with partners CDH3 and GOLGA4): one triple wild type and one with an NF1 comutation." (PMID 32123303, 2020). "The observed post-treatment effect inducing over-expressions in both CDH3 and CDH15 is therefore neutralizing the loss of cell-cell dependent adhesion and influencing melanoma development and progression." (PMID 30485296, 2018). "In normal cells, CDH3 regulates cell growth and migration, but CDH3 may have opposing effects in tumors depending on type: CDH3 promotes tumorigenesis in pancreatic, breast, and gastric cancer but has the opposite effect in non-small cell lung carcinoma, liver cancer, and melanoma 6,7." (PMID 37151391, 2023). "More recently, the aberrant expression of P-cadherin (CDH3) and cadherin-11 (CDH11) have also been described in the context of different types of cancer such as in malignant melanoma, breast, gastric, lung, colorectal, and pancreatic cancer." (PMID 31373305, 2019). "There are several subtypes of cadherins, however type I cadherins are the most relevant to melanoma, and include: epithelial cadherin (E-cadherin, CDH1), present in epithelial cells, melanocytes and keratinocytes; neural cadherin (N-cadherin, CDH2); and placental cadherin (P-cadherin, CDH3)." (PMID 37181747, 2023).